ENSG00000296671 (novel transcript)
Gene: Long non-coding RNA gene on chromosome 2 (70,888,270 to 70,900,469, reverse strand). Ensembl gene ENSG00000296671.
Gene Ontology:
Biological process: regulation of cell cycle